SNORD9 (small nucleolar RNA, C/D box 9)
Synonyms: mgU6-53B
Gene: Small nucleolar RNA gene on chromosome 14 (21,392,150 to 21,392,253, reverse strand). Ensembl gene ENSG00000199436.
Gene Ontology:
Biological process: RNA processing
Cellular component: nucleolus
Homologues: Orthologues: chimpanzee SNORD9 (99% identical), macaque SNORD9 (96% identical), pig SNORD9 (86% identical), rabbit SNORD9 (85% identical). Paralogues in human: SNORD8 (76% identical).